UBE3A (ubiquitin protein ligase E3A)
Diseases named in the same sentence as UBE3A in open-access papers (continued):
Sharing a sentence is not in itself a finding about the gene and the disease.
Angelman syndrome (continued). "In Angelman syndrome, a disorder highly penetrant for ID, beta power is reduced in cases caused by 15q11-q13 deletion relative to cases with etiologies that mainly impact UBE3A, suggesting a positive relationship between beta power and GABRB3/GABRA5/GABRG3 copy number." (PMID 31312421, 2019). "Moreover, the loss of function of maternally inherited UBE3A is also associated with Angelman syndrome (AS), a neurodevelopmental disorder with severe mental retardation along with autistic features, thus making UBE3A a potential candidate gene to be studied for better understanding of autism." (PMID 30568575, 2018). "Angelman syndrome (AS), characterized by severe mental retardation, developmental delay, ataxia, seizures, speech impairment, and happy disposition, is caused by mutation of E3 ubiquitin ligase UBE3A; a critical enzyme involved in proteasome-mediated protein degradation." (PMID 27232889, 2016). "Furthermore, mutations in UBE3A also cause Angelman syndrome (10–15 %)." (PMID 26583054, 2015). "The identification of these Dube3a targets is the first step in identifying new pathways regulated by UBE3A in humans that are responsible for the underlying defects in both Angelman syndrome and duplication 15q autism and may reveal new therapeutic targets for the treatment of these disorders." (PMID 23626758, 2013). "As an example, the ubiquitin ligase Ube3A is associated with human cognitive defects, including Angelman syndrome, and it has been hypothesized that defective degradation of different Ube3A substrates, such as Arc, might contribute to the Angelman clinical manifestations." (PMID 22779007, 2012). "Most of our understanding of Angelman syndrome pathophysiology comes from the maternal UBE3A knockout mouse models, which has been instrumental in uncovering key molecular and neurological features of the disorder." (PMID 40956516, 2025). "Activating paternal UBE3A for treating Angelman syndrome and manipulating UBE3A activity in conditions like Dup15q and neurodegenerative diseases are promising and worthwhile." (PMID 40076922, 2025). "In Angelman Syndrome, a neurodevelopmental disorder characterized by developmental delay, intellectual disability, seizures, and motor dysfunction, the UBE3A gene is typically inactivated in neurons through imprinting." (PMID 40469903, 2025). "For instance, in neurons, the lncRNA UBE3A-ATS can silence the paternal UBE3A gene in cis, a mechanism that is significant in neurodevelopmental disorders such as Angelman syndrome." (PMID 41244840, 2025). "When the UBE3A protein was supplied externally, it improved synaptic plasticity in brain sections of rats with Angelman syndrome and enhanced fear memory." (PMID 40076922, 2025). "The scientific community has primarily concentrated on unraveling the function of UBE3A and its role in the pathophysiology of Angelman Syndrome (AS) and disease-modifying treatments attempt to increase neuronal UBE3A expression." (PMID 40877933, 2025). "The UBE3A gene encoding the E6-AP HECT-type E3 ubiquitin ligase and loss-of-function mutation in the UBE3A has been shown to be a causative factor of Angelman syndrome, a neurodevelopmental disorder." (PMID 40299435, 2025). "UBE3A-dependent spine morphology has often been reported in individuals with Angelman syndrome and UBE3A overexpression." (PMID 40076922, 2025). "Preferred adjunctive applications of the KD include genetic epilepsies, such as SCN1A-related Dravet syndrome, TSC1/TSC2-related tuberous sclerosis complex, and UBE3A-related Angelman syndrome." (PMID 40290041, 2025). "Adaptive nanopore sequencing as a diagnostic method for imprinting disorders and episignature analysis revealed an intragenic duplication of Exon 6 and 7 in UBE3A (NM_000462.5) in a patient with relatively mild Angelman-like syndrome." (PMID 39095842, 2024).
Angelman syndrome (continued). "High levels of PEG10 have been implicated in the neurological diseases Angelman’s syndrome and ALS, where regulators of PEG10 abundance (UBE3A in Angelman’s, and UBQLN2 in ALS) are mutated and unable to control PEG10 levels." (PMID 39775359, 2024). "We recently reported that LAMTOR1 is a target of the UBE3A ubiquitin ligase, which is downregulated in Angelman syndrome (AS), thereby implicating changes in lysosomal distribution, function and mTOR signaling in the etiology of AS." (PMID 39650798, 2024). "UBE3A, also known as E6AP forE6-associated protein, is an E3 UBligase implicated in the development of cervical cancer and neurodegenerationsuch as Angelman syndrome." (PMID 36920305, 2023). "One study was identified that evaluated an Angelman syndrome model composed of an Ube3a (E3 ubiquitin-protein ligase) gene expressing lentivector in human-derived haemopoietic stem cells." (PMID 37240368, 2023). "Previous genetic investigations consisting of array-CGH, screening for Angelman syndrome (DNA methylation analysis and UBE3A sequence analysis), and mitochondrial DNA sequencing were negative." (PMID 36926521, 2023). "In most cases involving Angelman syndrome a section of maternal chromosome 15 that contains the UBE3A gene is deleted." (PMID 38248358, 2023). "Angelman syndrome is caused by maternal copy deletion, chromosome 15q11.2-q13 abnormalities or the E6-AP ubiquitin protein ligase (UBE3A/E6AP) gene mutation." (PMID 36768153, 2023). "As for the research on the role of UBE3A in the occurrence and development of human diseases, it is well known that UBE3A deletion will lead to the occurrence of Angelman syndrome." (PMID 37461021, 2023). "In Angelman syndrome, the authors suggested that restoring Ube3A function during the embryonic and early postnatal periods is likely more effective than restoring gene function during the adult phase." (PMID 37240368, 2023). "In a study assessing an Angelman syndrome model using Ube3a-expressing lentivectors in haemopoietic stem cells to deliver functional UBE3A, the authors suggested that their approach is not dependent on a critical time window." (PMID 37240368, 2023). "Three ongoing phase I clinical trials are assessing the safety of ASOs targeting a noncoding transcript (UBE3A-ATS) to activate paternal UBE3A gene expression in individuals with Angelman syndrome (NCT04259281, NCT04428281, and NCT05127226)." (PMID 36365206, 2022). "We applied the same model structure to a mouse model of Angelman syndrome (n = 41) to detect antisense oligonucleotide-mediated treatment effects on absolute delta activity and Ube3a expression." (PMID 35611307, 2022). "ICV injection of an antimir to miR-134 (Ant-134) reduced audiogenic seizure severity in Angelman syndrome (AS) mice carrying a maternal deletion of Ube3a (Ube3a m-/p+)." (PMID 36250017, 2022). "In this case, mouse models of Angelman syndrome help to identify the mechanistic consequences of alterations of Ube3a expression levels that result in Angelman syndrome when deficient versus autism when over-abundant." (PMID 35401134, 2022). "Currently in clinical trials are ASOs targeting Scn1a (Dravet Syndrome, Clinical Trial #NCT04442295) and Ube3a (Angelman Syndrome, Clinical Trial #NCT04259281)." (PMID 36183905, 2022). "Dysfunction of both FMR1 and UBE3A are known to cause syndromic forms of ID, fragile X syndrome (OMIM: 300624) and Angelman syndrome (OMIM: 105830) respectively." (PMID 33758288, 2021). "Our results reveal the novel role of UBE3A in the regulation of RA signalling and provide insight into potential therapeutic targets for Angelman syndrome." (PMID 33995501, 2021).
Angelman syndrome (continued). "Because Angelman syndrome is caused by the LoF mutations in maternal UBE3A, hippocampal injection of an AAV9 delivering the UBE3A gene has been used as a gene therapy in AS mice, where it was found to markedly improve associative learning." (PMID 32880951, 2021). "Secreted ZF activated the imprinted paternal Ube3a in a transgenic reporter mouse and ameliorated motor deficits in a Ube3a deletion Angelman Syndrome (AS) mouse." (PMID 35153670, 2021). "Angelman syndrome, characterized by developmental delay, seizures, and ataxia, is caused by maternal deficiency in the imprinted gene UBE3A (ubiquitin protein ligase E3A)." (PMID 33996898, 2021). "Angelman Syndrome (AS) is a severe neurodevelopmental disorder due to impaired expression of UBE3A in neurons." (PMID 32792659, 2021). "Angelman syndrome (AS, OMIM #105830) is an incurable neurodevelopmental disease caused by the loss of function of the maternal copy of ubiquitin–protein ligase E3A (UBE3A) and other genes on chromosome 15q11–13 region." (PMID 34203304, 2021). "By silencing UBE3A, CRISPR has helped to pinpoint the genetic switch of neural circuits and the causal gene for Angelman syndrome." (PMID 33791256, 2021). "The first identified member of this constantly growing family is the UBE3A gene encoding the E6-AP HECT-type E3 ubiquitin ligase and whose loss-of-function has been shown to cause Angelman syndrome more than twenty years ago." (PMID 34566579, 2021). "iPSC-derived organoids from Angelman syndrome patients exhibited early silencing of paternal UBE3A, and topoisomerase inhibitors can rescue the protein level of UBE3A." (PMID 34332630, 2021). "In this review article, we summarize recent findings on brain-expressed HECT-type E3 UBE3 ligases and their murine orthologues, comprising Angelman syndrome UBE3A, Kaufman oculocerebrofacial syndrome UBE3B and autism spectrum disorder-associated UBE3C." (PMID 33182779, 2020). "In mouse models of Angelman syndrome that lack Ube3a, dendritic spines present abnormal morphologies and reduced densities in the hippocampus and neocortex." (PMID 32982715, 2020). "Mice lacking the nuclear isoform but not mice lacking the cytosolic isoform displayed all major behavioural phenotypes and synaptic deficits also seen upon complete UBE3A knockout in the previous Angelman syndrome mouse model." (PMID 31988313, 2020). "Psychomotor regression is rarely seen or reported among individuals with Angelman syndrome, but there was some evidence for a linkage of psychomotor regression with UBE3A and its adjacent regions on chromosome 15." (PMID 32722525, 2020). "Alterations in UBE3A levels, either deletion or overexpression, culminate in severe neurodevelopmental disorders such as Angelman syndrome or autism, respectively." (PMID 32455880, 2020). "Herein, we report the generation and functional characterization of a novel model of Angelman syndrome by deleting the entire Ube3a gene in the rat." (PMID 32066685, 2020). "We investigated the cellular and molecular effects of Ube3a deletion in mouse embryonic fibroblasts (MEFs) and Angelman syndrome (AS) mouse model hippocampi." (PMID 32455880, 2020). "Some of the best-studied syndromic ASD genes are FMR1 (Fragile X syndrome), TSC (Tuberous sclerosis), and UBE3a (Angelman syndrome; Bourgeron, 2015; Sztainberg and Zoghbi, 2016)." (PMID 32982715, 2020). "In order to understand the consequences of UBE3A deletion in Angelman syndrome, a mouse model that carries the maternal deletion of exon 2 of the Ube3a gene was generated." (PMID 32455880, 2020). "The HECT domain E3 ubiquitin ligase E6AP (UBE3A) is critical for the development of human papillomavirus (HPV) associated cancers, the neurodevelopment disorder Angelman Syndrome, and some cases of autism spectrum disorders." (PMID 31971989, 2020).
Angelman syndrome (continued). "The complete characterization of the ubiquitination pathway of an UBE3A substrate is important due to the role of this E3 ligase in rare neurological disorders as Angelman syndrome." (PMID 31130875, 2019). "The Angelman syndrome disease gene ubiquitin-protein ligase E3A (UBE3A) and mental retardation disease gene ubiquitin specific peptidase, X-linked (USP9X) were also identified." (PMID 31703099, 2019). "For that reason, among the six DDI1 ubiquitination sites detected in the present study, our interest focused on the ones mediated by UBE3A, as it is likely that UBE3A-dependent ubiquitination events are altered in Angelman syndrome patients." (PMID 31130875, 2019). "As compared to training with massed trials, spaced training significantly improved learning in both the Ts65Dn trisomy mouse model of Down syndrome and the maternally inherited Ube3a mutant mouse model of Angelman syndrome." (PMID 31182707, 2019). "As its locus overlaps with UBE3A gene and promoter, thus SNHG14 prevents UBE3A expression and leads to neurogenetic disorders, such as Angelman syndrome." (PMID 30546117, 2019). "Another example is lncRNA Ube3a-ats, which has been targeted in mice by the administration of ASOs and which offers a potential therapeutic target for Angelman syndrome." (PMID 30466456, 2018). "The disruption of its activity leads to Angelman syndrome, while in turn the Angelman syndrome was described in ASD with CNVs and mutations in UBE3A gene." (PMID 29934975, 2018). "Individuals with Angelman syndrome show clear motor impairments, and impaired performance on the accelerating rotarod is the most frequently described phenotype in Ube3a mice." (PMID 30220990, 2018). "For instance, the reduced level of AMPARs found at excitatory synapses in a mouse model of Angelman syndrome (Ube3A knockout) has been explained by a greater abundance of Arc protein resulting from the lack of Ube3A-mediated ubiquitination." (PMID 29162813, 2017). "The loss of maternal genomic material at the 15q11.2-13 locus results in Angelman syndrome since normally, only the maternal copy of the Ube3A gene is active in the brain." (PMID 27458336, 2016). "Impaired motor learning was reported in several ASD mouse models such as GABRB3, Ube3a (Angelman's syndrome) and NF1 (Neurofibromatosis type 1) mice." (PMID 26973485, 2016). "The UBE3A gene is part of the imprinted Prader-Willi/Angelman syndrome locus (PWS/AS locus) on chromosome 15q11q13." (PMID 27484051, 2016). "To create a human neuronal model for Angelman syndrome, we reprogrammed dermal fibroblasts of a patient carrying a defined three-base pair deletion in UBE3A into induced pluripotent stem cells (iPSCs)." (PMID 27484051, 2016). "Conversely, a loss of expression of the preferentially maternally expressed UBE3A gene in this region leads to Angelman syndrome (AS), an entirely different clinical disorder." (PMID 26062517, 2015). "In mouse models of both Angelman syndrome (decreased Ube3a) and Duplication 15q autism (elevated Ube3a) there are defects in glutamatergic synaptic transmission." (PMID 25948754, 2015). "In a mouse model of Angelman syndrome, hippocampal injection of recombinant adeno-associated virus serotype 9 (AAV9) carrying a cDNA of the mouse Ube3a produced localized restoration of Ube3a to wild-type levels." (PMID 24946931, 2014). "An attractive alternative approach for Angelman syndrome is the reactivation of the intact but silent paternal copy of UBE3A that exists in almost all affected individuals." (PMID 24946931, 2014). "Together, our results indicate UBE3A, an E3 ubiquitin ligase previously implicated in HPV-tumorigenesis and Angelman Syndrome, as a conserved and integral part of the circadian clock feedback loop." (PMID 24728990, 2014). "Molecular evaluations have also included normal Angelman syndrome methylation analysis, ubiquitin-protein ligase E3A (UBE3A) sequence analysis, and screening using a mitochondrial DNA point mutation panel." (PMID 23866855, 2013).
Angelman syndrome (continued). "In the present study, we continue evaluating Ube3a-ATS as a potential therapeutic target for treating Angelman syndrome." (PMID 24385930, 2013). "While the E3 ligase Ube3A is widely known for its role in the Prader-Willi and Angelman syndromes, rare forms of mental retardation, Ube3A has also recently been implicated in regulation of dendritic arbor growth in fruit flies." (PMID 23476809, 2013). "Mutation of several ubiquitin ligases and DUBs is linked to neurological diseases, including Parkin and UCH-L1 in Parkinson's Disease, Ube3A in Angelman's Syndrome, and USP14 in ataxia." (PMID 23316392, 2012). "Angelman syndrome has been successfully modeled in mice by inactivation of the maternal copy of Ube3a." (PMID 21826280, 2011). "To summarize, the data presented here showed that the Angelman syndrome protein UBE3A interacts with primary microcephaly protein ASPM and, like ASPM and other MCPH proteins, localizes to centrosomes." (PMID 21633703, 2011). "Given this scenario, we screened a human fetal brain library with an ASPM C-terminus bait and identified Angelman syndrome (AS) gene product UBE3A as an interacting partner." (PMID 21633703, 2011). "One of the novel duplications (proband 3) is ~1 Mb in size adjacent to the UBE3A gene, which is the gene responsible for Angelman syndrome." (PMID 18925931, 2008). "Expression studies therefore show that UBE3A (the Angelman syndrome gene) is biallelically expressed in marsupial and monotreme brain." (PMID 17069464, 2006). "The four causes of Angelman syndrome are 1) maternal deletion of 15q11.2q13, 2) paternal UPD15 3) mutations in UBE3A 4) mutations leading to imprinting errors of this region." (PMID 15655077, 2005). "Deletions of UBE3A have been demonstrated to cause Angelman syndrome, in the absence of methylation abnormalities." (PMID 39587356, 2025). "For instance, the specific deletion of UBE3A in the nucleus has been shown to replicate the characteristics of traditional UBE3A null animals, reflecting the seizure and learning deficits observed in patients with Angelman syndrome." (PMID 40076922, 2025). "Interestingly, UBE3A upregulation is more pronounced in the nucleus, where the nuclear form of UBE3A is thought to be the primary factor contributing to Angelman syndrome." (PMID 40076922, 2025). "Angelman syndrome (AS) is a rare genetic neurodevelopmental disorder caused by the absence of a functional UBE3A gene, leading to developmental, behavioral, and medical challenges." (PMID 40200228, 2025). "Some PNN proteins may be substrates of UBE3A that accumulate in the brains of individuals with Angelman syndrome." (PMID 40076922, 2025). "Moreover, our findings illustrate that treatment with (S)-PHA533533 increases UBE3A protein levels in mature iPSC-derived human neurons from an Angelman syndrome patient (ASdel1-0 neurons), as confirmed through western blot and immunocytochemistry assays." (PMID 38977672, 2024). "This study addresses, for the first time, the involvement of UBE3A in mitochondrial function during the embryonic development of Angelman syndrome, and the critical role of ROS in controlling the fate of neural stem and progenitor cells in AS brain development." (PMID 36991133, 2023). "Other evidence from an Angelman syndrome model using a Ube3a-expressing lentivectors in haemopoietic stem cells showed that Ube3a function could be restored beyond the typical early post-natal period." (PMID 37240368, 2023).